PEAK1 (pseudopodium enriched atypical kinase 1)
Diseases named in the same sentence as PEAK1 in open-access papers (continued):
Sharing a sentence is not in itself a finding about the gene and the disease.
colitis (1 paper, 2025). Inflammation of the colon. "In mice, Peak1 deficiency increases intestinal epithelium permeability and exacerbates inflammation in experimentally induced colitis models." (PMID 40707483, 2025). "To investigate a possible involvement of PEAK1 in intestinal inflammation, we induced colitis by administering mice with 2% Dextran Sulfate Sodium (DSS) for 7 days, followed by switching to sterilized water." (PMID 40707483, 2025). "In this study, we demonstrate that Peak1-/- mice exhibit increased intestinal tight junction-dependent permeability and enhanced vulnerability to DSS-induced colitis." (PMID 40707483, 2025). "Although Peak1-/- mice did not develop spontaneous intestinal inflammation, they displayed worsened symptoms following colitis induction with 2% DSS compared to WT mice." (PMID 40707483, 2025). "Functionally, we demonstrated that the absence of PEAK1 disrupts tight junction strands in intestinal epithelial cells, augmenting intestinal permeability and compromising resistance to DSS-induced colitis." (PMID 40707483, 2025).
gastric tumors (1 paper, 2021). "Negative expression of PEAK1 in gastric tumors and its relationship with tumor grade, invasion, and lymph node metastasis showed the role of this gene in epithelial to mesenchymal transition (EMT)." (PMID 34479583, 2021).
invasive breast carcinoma (1 paper, 2018). A carcinoma that infiltrates the breast parenchyma. "We found that PEAK1 and VEGFR2 mRNA expression are highly correlated in 17 out of 32 cancer types including invasive breast carcinoma." (PMID 29872538, 2018).
melanoma (1 paper, 2021). A malignant, usually aggressive tumor composed of atypical, neoplastic melanocytes. "In the present study, enforced PEAK1 inhibited E-cadherin expression, and promoted vimentin expression and PEAK1 knockdown promoted E-cadherin expression, and reduced vimentin expression in melanoma cells, suggesting that PEAK1 is associated with invasion and metastasis through regulating EMT." (PMID 34365903, 2021). "In the study, we aimed to determine the role and mechanisms of PEAK1 in regulating cell invasion and metastasis in melanoma cells in vitro and in vivo." (PMID 34365903, 2021). "In the study, we investigate the therapeutic effect of PEAK1 on melanoma cells in vitro and in vivo." (PMID 34365903, 2021). "Enforced PEAK1 expression increased Ki-67 index, and PEAK1 overexpression increased Ki-67 index, indicating the oncogenic role of PEAK1 on melanoma." (PMID 34365903, 2021). "We used a lentiviral vector to express short hairpin RNAs (Lv-PEAK1 shRNA) for inhibiting PEAK1 expression in the melanoma SKMEL28 cells." (PMID 34365903, 2021). "PEAK1 expression was detected in melanoma cell lines (SKMEL-1, SKMEL-2, SKMEL-19, SKMEL-28) by western blot assay." (PMID 34365903, 2021). "The results showed that enforced PEAK1 expression facilitated melanoma cell growth, invasion and metastasis via activating JAK/STAT3 signals, and PEAK1 knockdown inhibited melanoma cell growth, invasion and metastasis via inactivating JAK/STAT3 signals." (PMID 34365903, 2021). "Here, we found that downregulation of PEAK1 inhibited melanoma cell invasion, migration, and proliferation, and enforced PEAK1 expression promoted melanoma cell invasion, migration, and proliferation." (PMID 34365903, 2021). "We also found that targeting JAK/STAT3 signaling reversed PEAK1-induced effects, which provided a novel therapeutic target for melanoma." (PMID 34365903, 2021). "A full-length PEAK1 gene was cloned into the pcDNA 3.1 (+) plasmid and used to infect the melanoma SKMEL19 cells." (PMID 34365903, 2021). "Further work demonstrated that P6 (500 nM) treatment reversed PEAK1-induced effect in melanoma cells." (PMID 34365903, 2021). "The effect of PEAK1 on melanoma progression in vivo was also evaluated." (PMID 34365903, 2021). "In addition, PEAK1-induced effect in melanoma cells was reduced using U6 to inhibit JAK/STAT3 signal." (PMID 34365903, 2021). "We then investigated possible pathways by which PEAK1 could be involved in melanoma." (PMID 34365903, 2021). "However, the role and mechanisms of PEAK1 in melanoma invasion is still unknown." (PMID 34365903, 2021). "In this study, enforced PEAK1 expression induces EMT and promotes cell growth and metastasis in vitro and in vivo in melanoma cells through activating JAK/STAT3 signaling." (PMID 34365903, 2021). "Therefore, targeting PEAK1 might be an effective therapeutic strategy for patients with melanoma." (PMID 34365903, 2021). "On the contrary, PEAK1 overexpression promotes JAK/STAT3 signaling, thereby increasing melanoma cell invasion, migration, and proliferation." (PMID 34365903, 2021). "Since PEAK1 has the ability to induce EMT and promote cancer cell metastasis, it is speculated that PEAK1 has a similar effect on melanoma cells." (PMID 34365903, 2021). "Furthermore, targeting PEAK1 significantly decreases EMT and metastasis in melanoma cells through inhibiting JAK/STAT3 signaling." (PMID 34365903, 2021). "PEAK1 promotes tumorigenesis and metastasis via activating JAK/STAT3 signals, and PEAK1 knockdown reduced tumorigenesis and metastasis in melanoma via inactivating JAK/STAT3 signals, providing a novel therapeutic strategy for melanoma treatment." (PMID 34365903, 2021). "Our findings reveal that enforced PEAK1 could activate JAK/STAT3 signal and promote EMT in melanoma cells." (PMID 34365903, 2021).
metastasis (1 paper, 2022). The spread or migration of cancer cells from one part of the body (where they first appeared) to another. "Links between PEAK1 expression and the clinicopathological characteristics in PTC patients were determined Positive PEAK1 expression was associated with TNM stage, lymph node metastasis, extrathyroidal Invasion and high ATA risk, but not related with persistence/recurrence." (PMID 35996515, 2022).
ovarian carcinoma (1 paper, 2020). A malignant neoplasm originating from the surface ovarian epithelium. "PEAK1 overexpression promoted proliferation, migration, and invasion and inhibited apoptosis of ovarian cancer cells." (PMID 32167655, 2020). "Our study also confirmed that PEAK1 expression was high in ovarian cancer tissues and was mainly distributed in the cytoplasm." (PMID 32167655, 2020). "After PEAK1 overexpression, the proliferation rate of ovarian cancer cells and the number of migrating and invading cells both significantly increased, and the apoptosis rate of cells significantly decreased." (PMID 32167655, 2020). "Our results showed that CDC5L (without 3′‐UTR) overexpression reversed the inhibition of malignant behaviors of ovarian cancer cells by miR‐542‐3p and increased the expression levels of PEAK1, p‐ERK1/2, and p‐JAK2." (PMID 32167655, 2020). "Further detection of PEAK1 protein expression in CDC5L‐overexpressing and ‐silenced ovarian cancer cell lines showed that PEAK1 protein expression level significantly increased after CDC5L overexpression, whereas PEAK1 protein expression level significantly decreased after CDC5L silencing." (PMID 32167655, 2020). "The circ‐PGAM1/miR‐542‐3p/CDC5L/PEAK1 pathway played an important role in the progression of ovarian cancer and might be a novel therapeutic target for ovarian cancer." (PMID 32167655, 2020). "Furthermore, PEAK1 played a tumor‐promoting role in ovarian cancer cells." (PMID 32167655, 2020). "Furthermore, the circ‐PGAM1/miR‐542‐3p/CDC5L/PEAK1 axis might be a potential therapeutic target in ovarian cancer." (PMID 32167655, 2020). "PEAK1 overexpression activated the ERK1/2 and JAK2 signaling pathways to promote malignant progression of ovarian cancer." (PMID 32167655, 2020). "PEAK1 overexpression activated ERK1/2 and JAK2 signaling pathways and promoted malignant biological behaviors of ovarian cancer cells." (PMID 32167655, 2020). "We further showed that CDC5L promoted PEAK1 expression in ovarian cancer cells, indicating that CDC5L can act as a transcription factor to activate PEAK1 expression." (PMID 32167655, 2020). "Since PEAK1 was activated by CDC5L and miR‐542‐3p regulated the malignant biological behaviors of ovarian cancer cells through targeting the CDC5L 3′UTR, we next examined whether PEAK1 and downstream pathways were involved in the tumor‐suppression effect of miR‐542‐3p on ovarian cancer cells." (PMID 32167655, 2020).
cancer (29 papers, 2010 to 2025). A tumor composed of atypical neoplastic, often pleomorphic cells that invade other tissues. "Several groups including ours have linked PEAK1_3 pseudokinases to cancer (i.e., PEAK1/Sgk269, PEAK2/Pragmin/SgK223/NACK, and PEAK3/C19orf35)." (PMID 35740644, 2022). "The PEAK1 and 2 pseudo-kinases have emerged as important components of the protein tyrosine kinase pathway implicated in cancer progression." (PMID 34944965, 2021). "While aberrant expression of PEAK1 has been linked to cancer progression, its normal physiological role in vertebrate biology is not known." (PMID 29872538, 2018). "PEAK1, a novel human pseudokinase, has recently been implicated in cancer pathogenesis." (PMID 40148311, 2025). "PEAK1 (Pseudopodium-Enriched Atypical Kinase One) is an actin cytoskeleton- and focal adhesion-associated pseudokinase that promotes cell state plasticity and cancer metastasis by mediating growth factor-integrin signaling crosstalk." (PMID 34239043, 2021). "The protein encoded by the PEAK1 may play a role in the regulation of cell proliferation and cancer metastasis 72-74." (PMID 33854600, 2021). "In addition, PEAK1 is strongly implicated in the progression of a variety of cancers." (PMID 39984440, 2025). "However, little is known about whether this amino acid substitution can affect kinase catalytic activity or whether this PEAK1 residue (and/or others) may be mutated in human cancers to confer full catalytic activity." (PMID 21301050, 2010). "Most research has focused on the functions of PEAK1 in pathological conditions, particularly cancer, with minimal attention given to its role in diseases other than cancer." (PMID 40707483, 2025). "While PEAK1’s roles in cancer cells are well documented, its regulatory mechanisms and physiological functions in non-cancerous contexts require further exploration." (PMID 40707483, 2025). "While its role in the brain remains largely uncharacterized, these results extend the potential relevance of Peak1 beyond cancer biology and point to its possible involvement in neuronal adaptation to sleep-related stress." (PMID 40918978, 2025). "The PEAK1 and Pragmin/PEAK2 pseudo-kinases have emerged as important components of the protein tyrosine kinase pathway implicated in cancer progression." (PMID 34944965, 2021). "Like AXL, PEAK1 expression correlates in many cancer models with mesenchymal features, disease relapse, and therapy resistance." (PMID 32681075, 2020). "In summary, PEAK1 is critical for tumor development and is possibly a new therapeutic target for cancer." (PMID 29449544, 2018). "These accumulating data indicate that PEAK1 serves as a scaffold to integrate and transmit multiple signals from the extracellular environment to the interior of cancer cells." (PMID 29872538, 2018). "The fact that PEAK1 drives both tumor progression and mediates tumor-induced angiogenesis makes it a promising therapeutic target for cancer and other angiogenesis-dependent disorders." (PMID 29872538, 2018). "In fact, our statistical analysis using the TCGA data set showed elevated PEAK1 mRNA expression in normal tissue compared with cancer tissue." (PMID 29449544, 2018). "PEAK1 promotes tumor growth/metastasis and therapy resistance in human cancers via its regulation of the actin cytoskeleton and Src, KRas and ErbB2 signaling pathways." (PMID 26267863, 2015). "Our previous work has shown that PEAK1 promotes therapy resistance in human cancers, and others have reported that EMT induction can also drive therapy resistance." (PMID 26267863, 2015). "It will be important for future studies to characterize the role of PEAK1 during early, proliferative versus late, metastatic stages of cancer progression." (PMID 21301050, 2010). "Although the function of many phosphorylated-tyrosine sites on PEAK1 is unknown, Src is a well-established PEAK1 kinase in cancer cells." (PMID 40707483, 2025).
cancer (continued). "Furthermore, our research has shown underexpression of genes associated with tumor formation and cancer cell migration, including AKT Serine/Threonine Kinase 3 (AKT3), Serine/Threonine Kinase (ATM) and Pseudopodium Enriched Atypical Kinase 1 (PEAK1) gene." (PMID 38074096, 2023). "Remarkably, PEAK1 exerts significant influence in the realm of cancer." (PMID 38136890, 2023). "The domain structure of PEAK1 has predicted consensus binding and/or substrate sites for Src, Erk, Shc and Crk and can operate within Src-p130Cas-Crk-Paxillin and Ras-Raf-Erk signaling pathways to regulate cell proliferation, migration and cancer progression." (PMID 34365903, 2021). "Previous and our findings suggest that future directions may explore the potential role of cannabis plants in cancer research focusing on the PEAK1 pathways." (PMID 34500744, 2021). "PEAK1 upregulation has been observed in various cancers, and PEAK1 may function as an oncogene involved in tumorigenesis and cancer progression." (PMID 30038287, 2018). "Interestingly, GATA2 mRNA expression is not significantly correlated with either PEAK1 or VEGFR2 mRNA in most cancer types, which is consistent with our findings that PEAK1 regulates GATA2 protein degradation at the post-translational level." (PMID 29872538, 2018). "However, compared with PEAK1 overexpression, PEAK1 knockout showed the opposite effects on signaling activation, genes expression and cancer characteristics." (PMID 30038287, 2018). "However, to fully understand PEAK1′s role in cancer it is necessary to understand its normal physiological role in the body, which is not yet known." (PMID 29872538, 2018). "While additional work is needed to assess the functional relevance of both PEAK1 and MST1R in the context of KRas wild type cancers, these data predict that PEAK1 may be a more potent driver of initiation and progression under these wild type KRas conditions." (PMID 27602776, 2017). "In addition, we identify CAMK2D and CAMK2G as downstream effectors of PEAK1 in TNBC and ‘repurposing’ of the second generation CAMK2 inhibitor RA306 as a potential therapeutic strategy against oncogenic PEAK1 signalling in poor prognosis human cancers such as TNBC." (PMID 39984440, 2025). "Although these associations are correlative, they are consistent with findings in cancer models, where Peak1—a non-receptor tyrosine kinase associated with the cytoskeleton—mediates signaling crosstalk between transforming growth factor beta receptors and integrin/Src/MAPK pathways." (PMID 40918978, 2025). "Thus, PEAK1 levels or a PEAK1 gene expression signature may be important indicators for determining when TGFβ blockade is a viable anti-cancer treatment option." (PMID 26267863, 2015). "Notably, this underscores the importance of understanding the role of PEAK1 in human cancers." (PMID 21301050, 2010). "Overall, these data identify RA306 as a potential therapeutic strategy against the PEAK1/CAMK2 axis in TNBC and potentially other human cancers." (PMID 39984440, 2025). "In the context of cancer, eIF5A hypusination facilitates translation elongation of MYC and regulates the focal adhesion kinase PEAK1, both of which contribute to tumor growth." (PMID 38689086, 2024). "PEAK1 was specifically expressed in NK cells of HS-PHT sample, that plays a role in the regulation of cell migration, proliferation and cancer metastasis." (PMID 35865544, 2022). "Therefore, deregulated expression of the PEAK1-VEGFR2 axis may contribute widely to human cancers." (PMID 29872538, 2018). "Using The Cancer Genome Atlas (TCGA) database and bioinformatics, we examined the expression correlations of PEAK1 mRNA and VEGFR2 mRNA levels across 32 different human cancers." (PMID 29872538, 2018). "Importantly, PEAK1 is a critical regulator of multiple cellular processes and its tyrosine kinase domain may likely provide a novel therapeutic target for controlling aberrant cellular functions that lead to cancer." (PMID 21301050, 2010).
cancer (continued). "Recent research has revealed the PEAK1 signature, which becomes elevated under conditions of moderate to severe hypoxia, correlating with heightened MYC expression and a robust Ki67-proliferation index in cancer cells." (PMID 38136890, 2023). "The genes preferentially mutated in metastases were MYLK, PEAK1, SLC2A4RG, EVC2, XIRP2, PALB2, and ESR1 (five of which are not significantly mutated in any type of human primary cancer)." (PMID 34771579, 2021). "A study by Agajanian and co-workers (2015) showed that the Src-regulator PEAK1 mediates the shift of TGF-ß responses from an anti-proliferative to pro-tumorigenic function, highlighting the importance of signaling pathway crosstalk during cancer progression." (PMID 34906074, 2021). "PEAK1 is a non-receptor tyrosine kinase that regulates the activity of Src kinase and plays an important role in the occurrence and development of malignant tumors." (PMID 33200656, 2020). "Finally, interrogation of human cancer databases revealed that PEAK1 and VEGFR2 mRNA expression are highly correlated in many human cancers (17 of 32)." (PMID 29872538, 2018). "Biochemically, PEAK1 interacts with Src, Shc1, Crk, and Grb2 adaptor proteins in the cytoplasm to convey signals from membrane receptor tyrosine kinases such as EGFR and ErbB2, which mediate cancer cell migration and proliferation." (PMID 29872538, 2018). "In addition, interrogation of cancer databases revealed that elevated levels of PEAK1 and VEGFR2 mRNA are highly correlated in many human cancers, suggesting that the regulation of the PEAK1-VEGFR2 axis contributes to this disease." (PMID 29872538, 2018). "More specifically, when PEAK1 is upregulated in the presence of fibronectin, TGFβ signaling can co-regulate Smad2/3 and MAPK signaling to promote EMT, tumor cell migration/proliferation and cancer metastasis." (PMID 26267863, 2015). "Collectively, our findings demonstrate that PEAK1 is a new non-receptor tyrosine kinase that operates within Src-p130Cas-Crk-Paxillin and Ras-Raf-Erk signaling pathways to regulate cell proliferation, migration and cancer progression." (PMID 21301050, 2010). "While protumour functions for PEAK1 were reported in CRC, the oncogenic role of PEAK2 in this cancer was not clearly established." (PMID 35740644, 2022).